UCP2 (uncoupling protein 2)
Diseases named in the same sentence as UCP2 in open-access papers (continued):
Sharing a sentence is not in itself a finding about the gene and the disease.
tumor (continued). "UCP2 expression is regulated by miRNAs that include miR-133a and miR-15a, both considered as tumour suppressor miRNAs downregulated in PDAC." (PMID 36672360, 2023). "UCP1 was associated with enhanced FAO and glutamine metabolism, while UCP2 with enhanced anti-tumor immunity." (PMID 35874806, 2022). "Under hypoxic conditions, similar to tumor core conditions, the overexpression of UCP2 in the lung adenocarcinoma cell line A549 showed anti-apoptotic properties." (PMID 36499405, 2022). "Overall, we argue that UCP2 transport-related regulations occur not only in a tumor context, but also in a healthy context." (PMID 36499405, 2022). "This means that researchers have only probed the role of UCP2 in tumor maintenance and progression, whereas the role of this transporter in tumor initiation is unexplored." (PMID 35008407, 2022). "A positive correlation between the expression level of UCP2 and glutamine dependence has been demonstrated in several human and murine tumor cell lines." (PMID 36499405, 2022). "Therefore, the loss of UCP2 may favor tumor cells that are less likely to metastasize." (PMID 36499405, 2022). "This review provides an overview of the latest published science linking mitochondrial UCP2 activity to the tumor context." (PMID 36499405, 2022). "Some researchers argue that forced UCP2 expression confers a survival advantage on tumors, while others have shown that UCP2 expression arrests tumor growth, oxidative stress, and angiogenesis." (PMID 35090503, 2022). "We found that MitoQ was able to reduce the expression of UCP2 in WAT in the tumor-bearing mice (−59%, p < 0.05)." (PMID 35392166, 2022). "Designing or synthesizing new molecules directly targeting UCP2 should be a priority in the coming years to counter tumor progression." (PMID 36499405, 2022). "Although these results suggest that UCP2 has an opposite function in tumor initiation and maintenance/progression, the biochemical function of UCP2 remains the same in both situations." (PMID 35008407, 2022). "Calcium signaling is therefore a finely regulated process that depends on the balance between mitochondria-ER binding and mitochondrial Ca2+ uptake via variations in UCP2 expression to optimally promote tumor development." (PMID 36499405, 2022). "The overexpression of UCP2 in JB6 P+ cells stimulated with the tumor inducer TPA (12-O-tetradecanoylphorbol 13-acetate) enhanced calcium signaling induced by PLCγ-1 upregulation." (PMID 36499405, 2022). "It was worth noting that UCP2 was expressed higher in tumor samples based on TCGA and GTEx, which was contrary to its immunohistochemical result." (PMID 36003146, 2022). "An important source of confusion regarding the evaluation of UCP2, particularly in respect to transcriptomic data from tumor cells, is its peculiar translational regulation due to constant repression." (PMID 36275699, 2022). "Because of this, UCP2 should be investigated at the protein level should clinicians wish to follow it as a tumor marker in the future." (PMID 33763373, 2021). "In head and neck, skin, prostate, and pancreatic tumor samples, the protein levels of UCP2 were significantly higher in tumor tissues than that in the adjacent normal tissues; but the protein levels of UCP2 was lower in non-small cell lung tumor tissues." (PMID 34481515, 2021). "In this context, important results were obtained in a study examining the relationship between UCP-2 and the tumor microenvironment (TME)." (PMID 34481515, 2021). "For example, UCP2 expression is upregulated in several tumor types as well as some chemo-resistant cell lineages." (PMID 34627389, 2021). "The central role of UCP2 in driving the metabolic switch in aggressive neoplasms, and its potential therapeutic implications have yet to be thoroughly investigated." (PMID 33763373, 2021).
tumor (continued). "While the link between glucose and inflammation has been well documented in the scientific literature, the effect on the tumor’s microenvironment of the metabolic shift accompanying UCP2 upregulation also warrants further investigation." (PMID 33763373, 2021). "Studies have demonstrated that mitochondrial uncoupling protein 2 (UCP2) leads to tumor resistance to multiple anticancer drugs by reducing ROS generated by mitochondrial metabolism." (PMID 32175074, 2020). "UCP2 overexpression is observed in tumor cells, which gives genipin, a UCP2 inhibitor, a potential anti-tumor activity mechanism." (PMID 32858815, 2020). "More interestingly, UCP2 acted as a tumor suppressor and altered glycolysis in addition to the mitochondrial effects in EACC." (PMID 29254145, 2017). "In contrast, 10 of 10 mice inoculated with UCP2 knockdown OE33 cells developed tumors which were uniformly much larger than the one control tumor." (PMID 29254145, 2017). "In this study, we provide new evidence that UCP2 plays a critical role in the regulation of the metabolic switch during skin tumorigenesis." (PMID 29221144, 2017). "In contrast, other reports suggest that UCP2 is a tumor suppressor and its re-expression is a potential therapeutic strategy." (PMID 29254145, 2017). "Analysis of The Cancer Genome Atlas (TCGA) database revealed an increase in UCP2 as well as in PRMT1 mRNA expression in several tumor tissues in comparison to adjacent normal tissue." (PMID 29113301, 2017). "Knockdown of UCP2 in NSCLC cell lines reduced the tumor inhibition rates of chemotherapeutic agents, whereas overexpression of UCP2 sensitized refractory cell lines to chemotherapy." (PMID 28042952, 2017). "Our data also demonstrate a potentially novel mechanism to understand UCP2's tumor-promoting role, which is through the AKT-dependent activation of PFKFB2 and thereby, the metabolic shift to glycolysis (the Warburg effect)." (PMID 29221144, 2017). "Immunohistochemical assessment of clinical samples showed that UCP2 expression was significantly lower in the tumor tissues of chemoresistant NSCLC patients than in those of chemotherapy-sensitive patients." (PMID 28042952, 2017). "Collagen 1A1 (COL1A1), RNA-binding and pre-mRNA Processing Factor (PRPF40A), and Uncoupling Protein 2 (UCP2) were identified as downstream effectors of cytoglobin (CYGB), which was shown implicated in tumour biology." (PMID 28258342, 2017). "We noted a significant reduction in clonogenicity, invasion, migration, and tumor formation and size with overexpression of UCP2." (PMID 29254145, 2017). "Because FLO-1 cells exhibited lower tumorigenicity compared with Esc2 cells, we chose Esc2 cells to test tumor volumes and incidence following UCP2 overexpression." (PMID 29254145, 2017). "Tumor volumes of subcutaneous xenografts established from Esc2 cells constitutively expressing UCP2 were significantly smaller than tumors derived from vector control cells." (PMID 29254145, 2017). "In Esc2 cells, although all mice had tumors at the end of experiment, most control xenografts whereas detectable within 2 weeks while UCP2 overexpressing cells exhibited delayed tumor formation." (PMID 29254145, 2017). "Apart from that no other associations were observed between COL1A1, PRPF40A or UCP2 mRNA expression and patients’ gender, age, survival, smoking history, TNM classification, and tumour histology and differentiation." (PMID 28258342, 2017). "When irradiated, some tumor cells have higher levels of the uncoupling protein UCP2 and mitochondrial proton leak, thereby lessening mtROS and conferring resistance to cytotoxic treatments." (PMID 26894978, 2016). "Our data indicate that in the context of HCC, miR-214 acts as a putative tumour suppressor by targeting UCP2 and defines a novel mechanism of regulation of UCP2." (PMID 27129291, 2016).
tumor (continued). "Cumulatively, our data indicate that in the context of HCC, miR-214 acts as a putative tumour suppressor by targeting UCP2 and defines a novel mechanism of regulation of UCP2." (PMID 27129291, 2016). "In HCT116, HT29 and HepG2, etc., over-expression of UCP2 plays an anti-apoptotic role by modulating the generation of intracellular ROS after tumor cells are exposed to chemotherapeutic agents." (PMID 22292025, 2012). "Our studies suggest the tumor promoting function of UCP2 in vitro and in vivo in a mouse xenograft model." (PMID 21935467, 2011). "To establish a cause-and-effect relationship between UCP2 over-expression and tumor development, we expressed UCP2 in MCF7 cells." (PMID 21935467, 2011). "The expression levels of both UCP2 and UCP3 mRNAs were increased, suggesting that energy expenditure is associated with tumor growth." (PMID 21954358, 2011). "We also describe that genipin, a small molecule extracted from the gardenia plant, reduces the tumor promoting properties induced by over-expression of UCP2." (PMID 21935467, 2011). "Among which, UCP2 is widely distributed in various tissues and critical for ROS regulation, as well as, survival of tumor cells." (PMID 20976134, 2010). "An activation of UCP2 and UCP3 gene expression associated with an increase of catalase activity has previously been reported in atrophied gastrocnemius muscles of tumour-bearing rats." (PMID 19462004, 2009). "In contrast, mRNA levels of peroxisome proliferators-activated receptor gamma coactivator-1alpha and uncoupling protein-2 were increased in white fat of tumour-bearing mice." (PMID 17047651, 2006). "Since EMT is known to facilitate tumor dissemination and confer therapy resistance, targeting UCP2 may represent a promising strategy for inhibiting these aggressive traits." (PMID 41403699, 2025). "Furthermore, activation of the FABP4/UCP2 axis is prominently observed in CAAs, where it regulates complex functions in tumor progression and drug responses." (PMID 39823981, 2025). "However, data show antigen stimulation increases UCP2, which is crucial for anti-tumor responses by CD8 T cells." (PMID 41367865, 2025). "In summary, UCP2 plays an active role in glutamine metabolism by transporting aspartate from the matrix to the cytosol for nucleotide synthesis and antioxidant production, thereby promoting tumor cell growth and survival." (PMID 39795950, 2024). "This suggests that deletion of UCP2 may contribute to tumor initiation by creating a pro-oxidative state." (PMID 39795950, 2024). "Conversely, highly malignant tumor cells promote UCP2 expression." (PMID 39707176, 2024). "Interestingly, UCP2 appears to play divergent roles: as a tumor suppressor in normal cells and as an oncogene in established tumors." (PMID 39795950, 2024). "Silencing UCP2 significantly reduced tumor growth in xenograft murine models." (PMID 39795950, 2024). "In summary, evidence from the literature suggests that UCP2 may act as a tumour suppressor during tumour initiation while it can have the opposite role as tumour promoter during progression, though exerting the same biochemical function at both stages." (PMID 36672360, 2023). "The upregulation of UCP2 in tumor cells has raised considerable attention." (PMID 37175829, 2023). "Several studies have shown the ROS control induced by UCP2 in established tumor cell lines." (PMID 36499405, 2022).
tumor (continued). "Thus, in this section, we will attempt to elucidate the role of UCP2 in a tumor context by successively examining its involvement in the oxidative stress, metabolic and immune reprogramming of a tumor." (PMID 36499405, 2022). "Naturally, these results lead us to wonder whether increased UCP2 expression is protective or deleterious for tumor development." (PMID 36499405, 2022). "Pathway analysis revealed a potential link between UCP2 expression and tumor immunity in BC." (PMID 35874806, 2022). "This suggested a tumor-suppressive role of UCP2 in tumorigenesis." (PMID 35008407, 2022). "Moreover, the induction of UCP2 in combination with immunotherapy (anti-PD1 antibody) resulted in reduced tumor volume and improved survival compared with anti-PD1 antibody alone." (PMID 36499405, 2022). "As both of these features are important aspects of tumorigenesis, we will discuss in the next section how UCP2 might regulate tumor development." (PMID 36499405, 2022). "UCP2’s implications on tumor metabolism warrants more investigation." (PMID 33763373, 2021). "Furthermore, we investigated the anti-tumor efficacy of combined treatment of UCP-2 inhibitor Genipin with trastuzumab in BT474 cell line." (PMID 34146128, 2021). "We sought to analyze if UCP2 expression alone would correlate with tumor grade." (PMID 33763373, 2021). "Conversely, by inducting this metabolic shift which increases glucose availability in the tumor microenvironment, UCP2 may also have a relationship to pro-inflammatory cascades which favor tumorigenesis and progression." (PMID 33763373, 2021). "On the other hand, whether the expression of UCP-2 plays a role in HER2 mediated tumor growth and UCP-2 modulator can enhance the treatment efficiency of trastuzumab have not been well studied." (PMID 34146128, 2021). "Tumour masses from mice injected with UCP2 (genipin) and mTOR inhibitors (everolimus) revealed a strong reduction in tumour volume and number of mitosis, associated with a marked cytosolic glycolytic enzyme glyceraldehyde 3-phosphate dehydrogenase (GAPDH) nuclear positivity." (PMID 29587429, 2018). "Hence, it is important to understand the molecular basis of UCP2 overexpression in tumor cell metabolism, differentiation, and survival." (PMID 29221144, 2017). "Finally, metabolic changes including UCP2 up-regulation and UCP2-mediated uncoupling of oxidative phosphorylation have been demonstrated in multidrug-resistant subclones of various tumor cell lines." (PMID 23966948, 2013). "Numerous studies have indicated that UCP2 expression is upregulated in several tumor types." (PMID 22292025, 2012). "When UCP2 was downregulated using a siRNA approach, cell transformation was suppressed, suggesting UCP2 may serve as a tumor promoter during early tumorigenesis." (PMID 21954358, 2011). "We hypothesized that genipin could suppress the tumor promoting property of UCP2 by inhibiting its expression and function." (PMID 21935467, 2011). "Our studies suggest that genipin can suppress tumor promoting function of UCP2." (PMID 21935467, 2011). "Since UCP-2 is thought to be involved in the detoxification of free radicals if LMF induced UCP-2 expression in tumour cells, it might attenuate free radical toxicity." (PMID 15026812, 2004). "If LMF induced UCP-2 expression in the tumour, this may be important in detoxifying free radicals, which are produced in excess during the process of cachexia." (PMID 15026812, 2004). "Many anticancer drugs such as adriamycin, bleomycin and mitomycin C exert their action through generation of reactive oxygen radicals, and induction of UCP-2 by LMF may protect tumour cells from their cytotoxic action." (PMID 15026812, 2004). "Several small-molecule mitochondrial uncouplers have demonstrated anticancer effects in preclinical models, although endogenous UCPs—particularly UCP2—are often upregulated in tumors, where they may support tumor growth by buffering ROS and increasing metabolic flexibility." (PMID 40983641, 2025).
tumor (continued). "Thus, we hypothesize that UCP2 overexpression could protect tumor cells from radiation-induced cell death by mitigating ROS accumulation." (PMID 41403699, 2025). "In addition, UCP2 silencing significantly reduced tumour size of KRAS-mutant PDAC xenografts." (PMID 36672360, 2023). "Whether UCP2 induces anti-tumor immunity through molecular functions other than uncoupling oxidative phosphorylation, needs further investigation, as these results may provide new insights into tumor immunity." (PMID 35874806, 2022). "Thus, UCP2 may exert a dual role and limit or accelerate tumor initiation and progression depending on bioenergetics resources, initial needs and metabolic fluxes." (PMID 36275699, 2022). "Additionally, because UCP2 correlates with tumor grade, monitoring serum protein levels in the future may allow clinicians a relatively minimally invasive marker to correlate with disease progression." (PMID 33763373, 2021). "The higher expression level of miR133a in tumor xenografts delivered with pre-miR133a as compared with that in tumor xenografts delivered with scramble and saline were validated by real-time PCR, which is concomitant with decreased expression of UCP-2 in mRNA and protein levels." (PMID 26107945, 2015). "However, the indication that UCP2 protects against tumours implies that a general reduction of UCP2 activity might have undesirable side effects." (PMID 24281083, 2010). "Studies investigating the expression and function of UCP1 and its homologs (UCP2 and UCP3) in various tumor types have yielded heterogeneous results." (PMID 40983641, 2025). "Mechanistically, it has been reported that miR-2909 can upregulate UCP2 expression by repressing the KLF4 gene, which is a tumour-suppressing gene downregulated in PDAC." (PMID 36672360, 2023). "The study concluded that the overexpression of UCP-2 and UCP-3 in the skeletal muscle was due to the anorexia induced by the burden of the tumor." (PMID 36900198, 2023). "Further mechanistic study showed that circUCP2 functioned as a ceRNA by sponging miR-149 and upregulating UCP2 expression, leading to NSCLC tumor progression." (PMID 37744277, 2023). "UCP1, UCP2, UCP3 and UCP5 expression levels correlated with a favorable prognosis and tumor progression." (PMID 35090503, 2022). "Therefore, we hypothesize that UCP2 may play a role in tumor cells in response to hypoxic stimuli." (PMID 22292025, 2012). "Moreover, UCP2 inhibition enhances IFN-γ production in patient-derived PBMCs and tumor-infiltrating lymphocytes." (PMID 41486584, 2026). "Uncoupling protein 2 (UCP2) reprograms the TME from immunosuppressive to immunostimulatory by increasing CXCL10 production, attracting T cells to the tumor, and normalizing tumor vasculature, which further improves T cell infiltration." (PMID 40872475, 2025). "TGFβ signaling negatively regulates UCP2, as demonstrated in tumor cells where low malignancy levels suppress gene transcription by recruiting TGFβ-induced SMAD4 to six repressive SMAD-binding elements (RSBEs, − 100 to − 354) on the UCP2 promoter." (PMID 39707176, 2024). "Notably, the silencing of UCP2 reduces glutaminolysis in both KRAS-mutant and KRAS wild-type cells, but only reduces the cell proliferation and tumour growth of KRAS-mutant cells." (PMID 36672360, 2023). "Nevertheless, no tumor invasion was detected, which questions the role of UCP-2 in the tumor microenvironment." (PMID 36900198, 2023). "Unfortunately, the effect of Ucp2 KO on glutamine utilization during tumor initiation in the CRC mice models was not investigated." (PMID 35008407, 2022). "The lack of T cells infiltrating the tumor resides also on the reduced expression of mitochondrial uncoupling protein 2 (UCP2) on tumor cells." (PMID 32509589, 2020). "In addition, treatment of PARP1-KO Jurkat cells with APO866 resulted in upregulation of 6 powerful antioxidant genes, including CAT and genes known to increase tumor cell survival such SIRT2 and UCP2." (PMID 31803365, 2019).